NCSTN (nicastrin)
Description:
Essential subunit of the gamma-secretase complex, an endoprotease complex that catalyzes the intramembrane cleavage of integral membrane proteins such as Notch receptors and APP (amyloid-beta precursor protein). The gamma-secretase complex plays a role in Notch and Wnt signaling cascades and regulation of downstream processes via its role in processing key regulatory proteins, and by regulating cytosolic CTNNB1 levels.
Synonyms: KIAA0253; APH2; ATAG1874
Tractability: Small molecule: a drug acting on it is in phase 2 or 3 trials; a structure with a bound ligand is known; a high-quality ligand is known; it belongs to a druggable protein family. Antibody: its Gene Ontology location is reachable by antibodies, with high confidence; UniProt predicts a signal peptide or a membrane-spanning region. PROTAC: ubiquitination databases record sites on it; its protein half-life has been measured; a small molecule that binds it is known.
Target class: Protease; Aspartic protease A22A regulatory subfamily; Aspartic protease; Aspartic protease A22A subfamily; Aspartic protease AD clan; Enzyme
Gene: Protein-coding gene on chromosome 1 (160,343,294 to 160,358,957, forward strand). Ensembl gene ENSG00000162736.
Subcellular location: Membrane; Cytoplasmic vesicle membrane; Melanosome
Subcellular location (Human Protein Atlas): Cytosol
Pathways (Reactome):
Signal Transduction: Activated NOTCH1 Transmits Signal to the Nucleus; NOTCH2 Activation and Transmission of Signal to the Nucleus; NOTCH3 Activation and Transmission of Signal to the Nucleus; NOTCH4 Activation and Transmission of Signal to the Nucleus; NRIF signals cell death from the nucleus; Noncanonical activation of NOTCH3; Nuclear signaling by ERBB4; Regulated proteolysis of p75NTR; TGFBR3 PTM regulation
Disease: Constitutive Signaling by NOTCH1 HD+PEST Domain Mutants; Constitutive Signaling by NOTCH1 PEST Domain Mutants
Developmental Biology: EPH-ephrin mediated repulsion of cells
Extracellular matrix organization: Degradation of the extracellular matrix
Immune System: Neutrophil degranulation
Metabolism of proteins: Amyloid fiber formation
Gene Ontology:
Molecular function: ATPase binding; endopeptidase activator activity; growth factor receptor binding; protein binding; protein-macromolecule adaptor activity; aspartic endopeptidase activity, intramembrane cleaving; endopeptidase activity; peptidase activity
Biological process: amyloid precursor protein catabolic process; amyloid precursor protein metabolic process; amyloid-beta formation; membrane protein ectodomain proteolysis; membrane protein intracellular domain proteolysis; Notch receptor processing; protein processing; proteolysis; cerebellum development
Cellular component: cytoplasmic vesicle membrane; endoplasmic reticulum; extracellular exosome; focal adhesion; gamma-secretase complex; Golgi apparatus; lysosomal membrane; membrane; plasma membrane; azurophil granule membrane; endoplasmic reticulum membrane; endosome membrane; Golgi membrane; early endosome; endomembrane system; lysosome; melanosome; presynaptic membrane; protein-containing complex; sarcolemma; secretory vesicle; synaptic membrane; synaptic vesicle
Genetic constraint (gnomAD): Loss-of-function variants: 22 observed, 91.57 expected, observed/expected ratio (o/e) 0.24, 90% interval 0.17 to 0.34. The upper end of that interval is the gene's LOEUF score, 0.34, which puts it in group 1 of 6, group 1 being the genes least tolerant of losing a copy. Missense variants: 693 observed, 930.71 expected, observed/expected ratio (o/e) 0.74, 90% interval 0.7 to 0.79. Synonymous variants: 306 observed, 345.88 expected, observed/expected ratio (o/e) 0.88, 90% interval 0.81 to 0.97.
Homologues: Orthologues: chimpanzee NCSTN (99% identical), macaque NCSTN (94% identical), guinea pig NCSTN (91% identical), dog NCSTN (91% identical), pig NCSTN (91% identical), mouse Ncstn (89% identical), rat Ncstn (89% identical), rabbit NCSTN (85% identical), tropical clawed frog ncstn (59% identical), Drosophila melanogaster Nct (31% identical), Caenorhabditis elegans aph-2 (24% identical).
Diseases named in the same sentence as NCSTN in open-access papers:
NCSTN is named in the same sentence as 55 diseases in open-access papers, as found by Europe PMC text mining. Sharing a sentence is not in itself a finding about the gene and the disease. The quoted sentences say what the papers report.
breast carcinoma (13 papers, 2013 to 2023). "Overexpression of NCSTN can regulate the properties of breast cancer stem cells and induce the epithelial-mesenchymal transition (EMT) by cleaving the Notch1 protein 69-71." (PMID 37928268, 2023). "NCSTN is significantly upregulated in breast cancer and induces epithelial-mesenchymal transition (EMT) through Notch1 cleavage." (PMID 36439123, 2022). "Previous studies have examined the upregulated expression level of NCSTN in breast cancer and demonstrated the oncogenic role of NCSTN in vivo and in vitro assays." (PMID 32631394, 2020). "Nicastrin modulates the epithelial to mesenchymal transition and tumorigenicity in breast cancer cells." (PMID 32117864, 2020). "NCSTN overexpression regulated the properties of breast cancer stem cells and induced epithelial-mesenchymal transition (EMT) via cleavage of Notch1." (PMID 32631394, 2020). "Previous study has revealed that NCSTN regulated breast cancer stem cell properties and growth via Notch/AKT pathway." (PMID 32631394, 2020). "Here, we investigated the contribution of Nicastrin and Notch signalling in endocrine-resistant breast cancer cells." (PMID 24919951, 2014). "Our finding suggest that targeting Nicastrin and/or Notch4 warrants further clinical evaluation as valid therapeutic strategies in endocrine-resistant breast cancer." (PMID 24919951, 2014). "It has also been demonstrated that Nicastrin stable knockdown induces Notch inhibition in basal-like breast cancer cells, sensitising them to anti-proliferative effects of EGFR inhibition." (PMID 24919951, 2014). "Nicastrin is highly expressed in breast cancers and confers worse overall survival in ERα-ve tumours." (PMID 24919951, 2014). "Our data suggest that targeting Notch4 and Nicastrin is a potential approach to reverse endocrine resistance in breast cancer patients." (PMID 24919951, 2014). "Indeed, it has been previously shown that NCSTN (nicastrin) is overexpressed in breast cancer, and its genetic depletion is sufficient to inhibit tumor growth in vitro and in vivo." (PMID 33808143, 2021). "In breast cancer, high Nicastrin is mainly observed in the ER+ subtypes." (PMID 30515368, 2018). "Targeting of Nicastrin affects breast cancer stem cells and inhibits tumor formation in vivo." (PMID 30515368, 2018). "This may account for our observation that changes in N-linked glycans in the MDAMB231 breast cancer cells with TMEM165KO yields a very different migration pattern of the glycoprotein NCSTN compared with the non-malignant HEK293T cells and the cervical cancer cell line HeLa." (PMID 32733646, 2020). "We tested two predicted OCN pairs in each cancer type, including NCSTN and DNM1, and NCSTN and OGT in liver cancer; CCNA2 and PTP4A1, and HIF1A and PARP1 in lung cancer; and CCNA2 and PTP4A1, and PLK1 and PTP4A1 in breast cancer." (PMID 31097707, 2019). "In support of a mechanistic role of EMT in tamoxifen resistance of breast cancer cells, over-expression of Pin-1, AKT, Nicastrin and Notch4, FoxM1, brachyury as well as modulation of several microRNAs has been reported." (PMID 26206152, 2015). "The increased NCSTN copy-number, due to 1q-gain, can enhance other transcriptional and post-transcriptional mechanisms, thus leading to hyper-activation of gamma-secretase and NOTCH signaling in breast cancer." (PMID 33808143, 2021). "Similarly, in an orthotopic model of breast cancer treated with the monoclonal antibodies 10C11 and 2H6 targeting NCSTN, no histological evidence of goblet cell hyperplasia was detected, while these effects were evident in a GSI-treated arm." (PMID 33003595, 2020). "Additionally, a set of 22 genes (located on chromosome 1) has been co-identified with Nicastrin amplification and breast cancer, however, these genes showed no clear Notch signature." (PMID 30515368, 2018).
Alzheimer disease (11 papers, 2010 to 2023). A progressive, neurodegenerative disease characterized by loss of function and death of nerve cells in several areas of the brain leading to loss of cognitive function such as memory and language. "For example, the Alzheimer Disease (AD)-associated proteins APP, BACE1, Nicastrin, Tau, APOE and TREM2 all have several N- and O-glycosylations." (PMID 37201132, 2023). "We demonstrate a reduction of membralin mRNA and protein levels in Alzheimer’s disease (AD) brain, the latter of which inversely correlates with nicastrin abundance." (PMID 29133892, 2017). "Nicastrin is the largest component of γ-secretase that is an intramembrane protease important in the development of Alzheimer’s disease." (PMID 26776682, 2016). "Alzheimer's disease is characterized by amyloid plaques, which are built by a high molecular weight protein complex containing presenilin (PS), nicastrin, Aph-1 and Pen-2; presenilins are thought to be important drug targets for this disorder." (PMID 22279562, 2012). "A key player in the development of Alzheimer's disease (AD) is the γ-secretase complex consisting of at least four components: presenilin, nicastrin, Aph-1 and Pen-2." (PMID 20126630, 2010). "Nicastrin is an obligatory component of the γ-secretase; the enzyme complex that leads to the production of Aβ fragments critically central to the pathogenesis of Alzheimer's disease (AD)." (PMID 21364883, 2011). "Genes of the GSC have an established role in the pathogenesis of both monogenic Alzheimer disease (primarily PSEN1) and familial HS (primarily NCSTN), although genetic studies of HS are still in their infancy and characterized by relatively small numbers." (PMID 36118898, 2022). "Another study reported nine somatic mutations in the amyloid beta precursor protein (APP), sortilin-related receptor 1 (SORL1), nicastrin (NCSTN) and microtubule affinity-regulating kinase 4 (MARK4) genes in patients with Alzheimer’s disease by next-generation sequencing (NGS)." (PMID 37834279, 2023).
hepatocellular carcinoma (6 papers, 2019 to 2025). A malignant tumor that arises from hepatocytes. "For example, the drug candidate nicastrin (NCSTN) is a ƴ‐secretase clinically relevant in breast invasive carcinoma and associated with worst OS of liver carcinoma." (PMID 31216110, 2019). "NCSTN can also cause nuclear translocation of β-catenin, initiating the transcription of the Zeb1 (transcription factor), leading to a malignant phenotype in hepatocellular carcinoma." (PMID 39634655, 2024). "NCSTN promotes the growth and metastasis of hepatocellular carcinoma cells by activating β-catenin in a Notch1/AKT-dependent manner." (PMID 41472131, 2025). "Some studies have found that overexpression of NCSTN can promote the proliferation of hepatocellular carcinoma in vitro, and down-expression of NCSTN can inhibit the growth of hepatocellular carcinoma." (PMID 39634655, 2024). "Intriguingly, several studies have proven that genome-wide liver carcinoma screening identified NCSTN as one of the 50 potential driver genes, and NCSTN is abnormally upregulated and frequently amplified in liver cancer." (PMID 32226312, 2020). "However, the independent effect of nicastrin (NCSTN), the largest constituent of the γ-secretase complex, on the progression of hepatocellular carcinoma (HCC) remains to be discovered." (PMID 32226312, 2020). "NCSTN can affect the Notch1 and AKT signaling pathways and is involved in the development of hepatocellular carcinoma." (PMID 37691920, 2023).
liver cancer (4 papers, 2019 to 2023). An epithelial or non-epithelial malignant neoplasm that arises from the liver. "We found COLEC10, GPAA1, CD5L, NCSTN, SNX27, GOLPH3L, and HIST2H2AC genes were associated with worst OS (HR < 1) in female liver cancer patients." (PMID 31216110, 2019). "However, whether NCSTN monoclonal antibodies could effectively act on liver cancer cells remains unclear." (PMID 32226312, 2020).
acne inversa (3 papers, 2020 to 2024). "Moreover, mutations on the genes of γ-secretase components such as PS1, Pen2, or Nicastrin that cause γ-secretase haploinsufficiency are reported to cause familial acne inversa and/or Dowing-Degos disease associated with acne inversa." (PMID 32438286, 2020).
invasive breast carcinoma (3 papers, 2019 to 2020). A carcinoma that infiltrates the breast parenchyma. "Studies have also demonstrated that anti-NCSTN monoclonal antibodies exert antitumour effects in invasive breast cancer cells." (PMID 32226312, 2020).
chronic myelomonocytic leukemia (2 papers, 2016 to 2020). A myelodysplastic/myeloproliferative neoplasm which is characterized by persistent monocytosis, absence of a Philadelphia chromosome and BCR/ABL fusion gene, fewer than 20 percent blasts in the bone marrow and blood, myelodysplasia, and absence of PDGFRA or PDGFRB rearrangement. "Inactivation of Notch signaling by targeting the γ-secretase complex member Nicastrin in mouse HSCs resulted in an aberrant accumulation of granulocyte/monocyte progenitors in peripheral blood, spleen and liver, diagnostic of the induction of chronic myelomonocytic leukemia (CMML)-like disease." (PMID 26936847, 2016).
colon cancer (2 papers, 2020 to 2022). "NCSTN was also the response of colon cancer to chemotherapy." (PMID 36439123, 2022).
COVID-19 (2 papers, 2022 to 2024). A disease caused by infection with severe acute respiratory syndrome coronavirus 2. "Both genes were also coenriched in the Notch pathway, TLE3, and NCSTN; nonetheless, CTBP1 significantly differed in the COVID-19 comparison group, whereas DTX3L was more significant in the PQ comparison group." (PMID 39301288, 2024).
lung carcinoma (2 papers, 2019 to 2025). "A LASSO regression model was constructed using the expression matrix of H1975 and H1975-BM51 cells, identifying AGO3, NCSTN, and PGK1 as hub genes associated with lung cancer BM." (PMID 40696604, 2025). "Transcriptome sequencing data from H1975 and H1975-BM51 cells were analyzed using LASSO regression to construct a lung cancer-BM model, identifying AGO3, NCSTN, and PGK1 as hub genes." (PMID 40696604, 2025).
memory impairment (2 papers, 2017 to 2019). "Given that our results indicate that membralin levels can influence nicastrin expression and consequent γ-secretase function, factors that dysregulate or attenuate membralin may contribute to the pathological events such as Aβ accumulation, plaque deposition and memory impairment in AD." (PMID 29133892, 2017).
triple-negative breast carcinoma (2 papers, 2014 to 2020). An invasive breast carcinoma which is negative for expression of estrogen receptor (ER), progesterone receptor (PR), and human epidermal growth factor receptor 2 (HER2). "We developed and fully characterized two mAbs against the extracellular domain of Nicastrin that reduce tumour and metastasis formation in vivo of triple-negative breast cancer cell lines (and submitted data)." (PMID 24919951, 2014). "Additionally, the specific monoclonal antibodies against NCSTN were evaluated in cellular and pre-clinical assays, which suggested a promising role of targeting NCSTN for the treatment of invasive triple negative breast cancer." (PMID 32631394, 2020). "We have previously shown that Nicastrin regulates the EMT process and stem cell content in triple-negative breast cancers partially through Notch1/Notch4 activation." (PMID 24919951, 2014).
angioleiomyoma (1 paper, 2018). A benign, slow-growing neoplasm that arises from the dermis or subcutaneous tissue. "Only six genes show significant differences between the angioleiomyoma types (ISL1, NCSTN, TCF7, WNT10A, WNT11, WNT7A) but their relative expression levels were very low, which indicates no biological relevance (< 0.4 compared to standardized reference gene index)." (PMID 29881541, 2018).
bladder cancer (1 paper, 2021). "Moreover, Kaplan–Meier survival analysis showed that higher levels of Presenilin 1 and Nicastrin expression (p < 0.05) were associated with significantly poorer overall survival in patients with bladder cancer." (PMID 34059639, 2021). "The data suggest that CPX downregulates the Notch pathway in bladder cancer cells by inhibiting the γ-secretase complex proteins Presenilin 1 and Nicastrin." (PMID 34059639, 2021). "On the other hand, we have observed that CPX binds γ-secretase complex proteins Presenilin 1 and Nicastrin to inhibit Notch signaling, suggesting that CPX targets the γ-secretase complex in bladder cancer cells." (PMID 34059639, 2021).
bladder tumor (1 paper, 2021). "Furthermore, IHC analysis of bladder tumor tissues demonstrated decreased staining for Notch 1, Presenilin 1, Hes1 and Nicastrin in mice treated with CPX-POM." (PMID 34059639, 2021).
chordoma (1 paper, 2013). Chordomas are rare malignant tumors arising from embryonic remnants of the notochord in axial skeleton. "Six genes (NOTCH2, NCOR2, CREBBP, JAG1, KAT2A and NCSTN) related to the Notch signaling pathway were upregulated in chordoma tissues." (PMID 23826111, 2013).
cognitive decline (1 paper, 2017). "Our focus here characterizing membralin-associated ERAD nicastrin degradation has led us to establish a role for membralin in Aβ-associated AD pathology and cognitive decline." (PMID 29133892, 2017).
familial Alzheimer disease (1 paper, 2019). A degenerative disease of the brain that causes gradual loss of memory, judgment, and the ability to function socially. "Presenilin-1 knockout lines display distinct phenotypes from intron 4 deletion lines, including reduced mature nicastrin, arguing against a simple loss-of-function mechanism for familial Alzheimer’s disease mutations." (PMID 32395715, 2019).
familial hidradenitis suppurativa (1 paper, 2025). "Additionally, loss of function mutations in PSEN1, PSENEN and NCSTN all cause familial hidradenitis suppurativa, a chronic inflammatory skin condition, further supporting a putative anti-inflammatory role of γ-secretase." (PMID 40542358, 2025).
folliculitis (1 paper, 2022). Inflammation of the hair follicles. "HS patients having underlying NCSTN variants appear to have a follicular-type HS, in which comedones, papules and folliculitis predominate." (PMID 35401657, 2022).
glioma (1 paper, 2019). A benign or malignant brain and spinal cord tumor that arises from glial cells (astrocytes, oligodendrocytes, ependymal cells).
Gliosis (1 paper, 2020). Gliosis is the focal proliferation of glial cells in the central nervous system. "Although the dosage of DEX used in this study significantly increases the body weight of the mice, it does not reduce or inhibit gliosis in nicastrin cKO mice." (PMID 33015377, 2020).
lung squamous cell carcinoma (1 paper, 2024). "For lung squamous cell carcinoma, 11 genes were causally related, comprising COPA, NCSTN, U91328.19, GABBR1, IER3, HLA-DQB1-AS1, HLA-DQB2, ANKRD26, PKD2L1, PSMA4 and RAD51C." (PMID 38834983, 2024).
myeloproliferative disease (1 paper, 2015). "Mice congenitally deficient in nicastrin, a nonredundant Notch-activating protease, develop a malignant myeloproliferative disease dominated by cells expressing elevated levels of transcription factors that control myeloid-specific genes such as Ncf1, cFms and Fcrg29." (PMID 26194095, 2015).
papillary adenocarcinoma (1 paper, 2008). A morphologic variant of adenocarcinoma. "While cytoplasmic Notch 1 is more highly expressed in the papillary adenocarcinoma, the members of the γ-secretase complex, PSN1 and nicastrin (NCSTN), which release its NICD, were highly expressed in the carcinoma tumors." (PMID 18811984, 2008).